ATM (ATM serine/threonine kinase)
Diseases named in the same sentence as ATM in open-access papers (continued):
Sharing a sentence is not in itself a finding about the gene and the disease.
laryngeal tumors (1 paper, 2020). "In contrast to laryngeal tumors in TCGA, our cohort contained recurrent focal copy loss in genes associated with DNA damage repair (ATM, ATR, and BRCA2)." (PMID 33105726, 2020).
Left ventricular dilatation (1 paper, 2021). Enlargement of the chamber of the left heart ventricle. "Relative to the PBS control group, left ventricular dilatation with reduced fractional shortening was partially, but significantly, suppressed in the ATM inhibitor-treated group, as was the HW/BW ratio." (PMID 33953175, 2021).
lentivirus infection (1 paper, 2019). Virus diseases caused by the Lentivirus genus. "Overexpression of miR-421 into C4–2/N-Myc cells by lentivirus infection suppressed ATM expression and abrogated the N-Myc-enhanced migration/invasion, suggesting that N-Myc-enhanced migration/invasion is mediated, at least partially, by miR-421/ATM pathway." (PMID 30657058, 2019).
lupus vulgaris (1 paper, 2025). A form of cutaneous tuberculosis. "We report the first globally documented case of lupus vulgaris in an A-T patient and identify a previously unreported ATM variant in our country, expanding the disease spectrum." (PMID 41044616, 2025).
Lymphadenopathy (1 paper, 2014). Enlargement (swelling) of a lymph node.
male infertility (1 paper, 2022). The inability of the male to effect fertilization of an ovum after a specified period of unprotected intercourse. "In addition, ATM mutations may also be implicated in male infertility due to defective spermatogenesis." (PMID 36437957, 2022).
malignant mesothelioma (1 paper, 2020). A malignant neoplasm of the pleura or peritoneum, arising from mesothelial cells. "Using whole exome sequencing of five WDPMs of the peritoneum, we have identified distinct mutations in EHD1, ATM, FBXO10, SH2D2A, CDH5, MAGED1, and TP73 shared by WDPM cases but not reported in malignant mesotheliomas." (PMID 32545767, 2020).
meningitis (1 paper, 2020). A disorder characterized by acute inflammation of the meninges of the brain and/or spinal cord. "However, so far, there are no scientific reports regarding the associations between EGF, ATM, CASP8 and meningitis." (PMID 33031061, 2020). "More significantly, all vital biotargets of calycosin-anti-meningitis were eventually identified, including EGFR, TNF, EGF, ATM, ESR1, CASP8, NGF." (PMID 33031061, 2020). "Markedly, all vital biotargets of calycosin-anti-meningitis are identified, and at least some of new anti-meningitis targets may include EGF, ATM, CASP8." (PMID 33031061, 2020).
mesenchymal tumors (1 paper, 2024).
Nephropathy (1 paper, 2020). A nonspecific term referring to disease or damage of the kidneys. "In conclusion, we identified a central role for ATM in the balance of DNA damage and repair in cisplatin nephropathy." (PMID 32157166, 2020).
neural tumors (1 paper, 2025). "Overall, by comparing to PA, we identified subtype-specific pathways in neural tumors: PAK signaling (PTPRD and PDGFRB) in GBM, regulation of CFTR activity pathway (PPP2R1A, RABEP1) in MBL, and ERK signaling (IRS4 and ATM) in NBL." (PMID 40768543, 2025).
neurotoxicity (1 paper, 2024). Toxicity that causes injury to the central or peripheral nervous system or damages its function. "Neurotoxicity was also induced by inhibitors of the DNA damage response proteins TDP1 and ATM (167 and 50, respectively), indicating that DNA repair is essential for neuronal survival in culture." (PMID 38550989, 2024).
nonalcoholic steatohepatitis (1 paper, 2017). "Recently, nonalcoholic steatohepatitis without ATM protein in the nucleus of the hepatocytes was showed in a liver biopsy in one A-T patient." (PMID 28778179, 2017).
oligodendroglioma (1 paper, 2021). A well-differentiated (WHO grade II), diffusely infiltrating neuroglial tumor, typically located in the cerebral hemispheres. "Next, we sought to explore the potential involvement of ATM/ATR in VM formation in oligodendrogliomas." (PMID 34483751, 2021). "IHC of pATM and pATR was performed on oligodendroglioma specimens to determine the activation of ATM/ATR." (PMID 34483751, 2021). "Besides, oligodendrogliomas with VM formation displayed higher pATM/pATR levels, suggesting the extra participation of ATM/ATR activation in VM formation." (PMID 34483751, 2021). "The possible involvement of ATM and ATR in VM formation offers new insights into the therapeutic targets for oligodendroglioma patients especially for refractory and drug-resistance ones." (PMID 34483751, 2021). "In summary, activation of ATM/ATR but not HIF1α shows a positive correlation with VM formation in oligodendroglioma patients." (PMID 34483751, 2021). "In this study, we evaluated phosphorylate ATM (pATM) and phosphorylate ATR (pATR) levels using semi-quantitative immunohistochemical (IHC) staining and analyzed the VM formation by histochemical double-staining in a cohort of 136 surgically excised oligodendroglioma specimens." (PMID 34483751, 2021).
oral cavity cancer (1 paper, 2011). A primary or metastatic malignant neoplasm involving the oral cavity. "Comparison of gene expression levels (2-ΔΔCT) of ATM and APC between patients with oral cavity cancer and healthy controls." (PMID 22414247, 2011).
oropharyngeal cancer (1 paper, 2021). Carcinoma, predominantly squamous cell, arising from the epithelial cells of the oropharynx. "Alterations in ATM, a DNA repair gene, have been reported in various cancers like prostate, lung, and oropharyngeal cancer." (PMID 34136393, 2021).
oropharyngeal tumor (1 paper, 2023).
Pancreatic cysts (1 paper, 2019). A cyst of the pancreas that possess a lining of mucous epithelium. "Six of the 27 mutation carriers (22%) had pancreatic cysts of unknown type detected, including 1 ATM carrier, 3 BRCA2 carriers, and 2 CDKN2A carriers." (PMID 32601617, 2019).
pancreatic disease (1 paper, 2021). "The present WGS, however, detected potentially pathogenic variants in the ATM, SUFU, DAB1, POLQ, MAP3K3, FGFBP3 and ACAD9 genes that co-segregated with pancreatic disease in single FPC families, and thus might predispose them to the disease." (PMID 34357098, 2021).
parvovirus infections (1 paper, 2024). "Interestingly, ATR- or ATM-dependent DNA damage responses are also induced by parvovirus infections and are important for viral DNA replication." (PMID 39541416, 2024).
peritoneal mesothelioma (1 paper, 2020). A benign or malignant mesothelial neoplasm that arises from the peritoneum. "Notably, we found WDPM specific mutations in EHD1, FBXO10, CHD5, MAGED1, ATM, and TP73 genes that were absent in peritoneal mesothelioma." (PMID 32545767, 2020).
pilomatricoma (1 paper, 2020). "The presence of ATM in BASC could hint to a link between the enhanced mutation rate of CTNNB1 in the analyzed pilomatricomas and the detected ATM germline mutation." (PMID 32155193, 2020). "Moreover, the wild type allele of ATM was retained in the pilomatricoma as well as in the pilomatrical carcinoma which suggests that biallelic functional inactivation of ATM did not play a role in the development of pilomatricoma and pilomatrical carcinoma." (PMID 32155193, 2020).
plasma cell neoplasm (1 paper, 2025). A clonal proliferation of immunoglobulin-secreting plasma cells. "In plasma-cell neoplasms, ATM pathway disruption has been associated with adverse cytogenetics and treatment resistance." (PMID 41378284, 2025).
plasmacytoma (1 paper, 2025). Plasmacytoma is a localized mass of neoplastic monoclonal plasma cells that represents approximately 5% of all plasma cell neoplasms. "In this report, we have provided a detailed genomic characterization of a rare skull-base plasmacytoma in the setting of germline ATM mutation, demonstrating that integrative molecular analyses can yield crucial insights into the pathogenesis and potential vulnerabilities of these tumors." (PMID 41378284, 2025).
pneumococcal infection (1 paper, 2010). Infections with bacteria of the species streptococcus pneumoniae.
Pruritus (1 paper, 2019). Pruritus is an itch or a sensation that makes a person want to scratch. "Symptoms of pruritus resulted associated at t1 with a 0.79-fold change of XPC and with a 1.01-fold change of ZMAT3; at t2 pruritus was associated with a 0.87-fold change of ATM, and a lower BCL2/BAX ratio (respectively, 0.76- vs. 1.15-fold change)." (PMID 31632918, 2019).
refractive error (1 paper, 2022). A defect in the focusing of light on the retina as in astigmatism, myopia, or hyperopia. "Our WES GWAS analysis and fine-mapping study implicated two novel genes as conferring susceptibility to refractive error (COL4A4 and ATM)." (PMID 35022715, 2022).
Respiratory tract infection (1 paper, 2017). An infection of the upper or lower respiratory tract. "Evidence also indicates that the main risk factor with regard to mortality is the possibility of respiratory tract infections in patients with hypomorphic mutations in ATM, although those with null mutations in “class A” disease have an increased risk of cancer at a younger age." (PMID 28488180, 2017).
Retinal dystrophy (1 paper, 2018). Retinal dystrophy is an abnormality of the retina associated with a hereditary process. "Inefficient regulation of ATM expression could be central to PCD and inhibition of ATM-activation could suppress PCD in retinal dystrophy patients." (PMID 30345028, 2018).
Richter syndrome (1 paper, 2019). Transformation of chronic lymphocytic leukemia into aggressive non-Hodgkin's lymphoma, usually diffuse large B-cell lymphoma (immunoblastic or centroblastic variant).
Salmonella Infections (1 paper, 2026). Infections with bacteria of the genus SALMONELLA. "Recombinant typhoid toxin or Salmonella infection recapitulated LYZ and APOC3 secretion in cultured cells, which involved ATM/ATR-dependent DDRs and confirmed observations in typhoid fever." (PMID 41326716, 2026).
schwannoma (1 paper, 2020). A benign, usually encapsulated slow growing tumor composed of Schwann cells. "Particularly, ATM, accounting for 33% of the samples, was the most frequently mutated cancer-related gene in schwannoma, followed by CHD4, FAT1, KMT2D, MED12, NF2, and SUFU (>20%)." (PMID 33193598, 2020).
serous cystadenocarcinoma (1 paper, 2014). A malignant serous cystic neoplasm usually involving the ovary or the pancreas. "High ATM protein expression was associated with serous cystadenocarcinomas (p = 0.021) and platinum resistance (p = 0.017)." (PMID 26674120, 2014). "High ATM expression was significantly associated with serous cystadenocarcinomas (p = 0.021), CA-125 response to chemotherapy (p = 0.017) and platinum resistance (p = 0.017)." (PMID 26674120, 2014). "We found that high ATM expression was associated with serous cystadenocarcinomas, poor response to chemotherapy and platinum resistance." (PMID 26674120, 2014).
spinocerebellar ataxia with axonal neuropathy (1 paper, 2016). "Mutations in ATM and TDP1 have been linked to neurodegenerative diseases known as ataxia telangiectasia (A-T) and spinocerebellar ataxia with axonal neuropathy (SCAN-1), respectively." (PMID 27181710, 2016).
squamous cell skin cancer (1 paper, 2018). "Here, we report for the first time an association between the missense variant Asp1853Asn in ATM (rs1801516) and increased risk of squamous cell skin cancer." (PMID 30194396, 2018).
steatosis (1 paper, 2023). Increased lipid within the cytoplasm of cells. "During the steatosis phase, there was low ATM activation, which caused mitochondrial dysregulation and greater DNA damage, in addition to reduced growth of the hepatocyte." (PMID 37147676, 2023).
T-cell neoplasms (1 paper, 2023). "The cooperativity between TCL1 family members and ATM is seemingly unique to T-PLL across the spectrum of T-cell neoplasms." (PMID 37569479, 2023).
testicular germ cell tumor (1 paper, 2019). A germ cell tumor arising from the testis. "In line with cell death critically depending on mtDNA-damage rather than nDNA-damage, apoptosis induction by cisplatin in testicular germ cell tumor cells does not require the nDNA-damage response mediating proteins ATM, ATR, or DNA-PK11." (PMID 31699970, 2019). "In line, cisplatin induced apoptosis even independent of nuclear DNA is illustrated by the fact that testicular germ cell tumor cells still undergo cisplatin induced apoptosis in the absence of key mediators of DNA damage response, such as ATM, ATR, or DNA-PK11." (PMID 31699970, 2019).
thymic tumours (1 paper, 2020). "Overall, the results are consistent with a model in which misrepair of TOP2-induced DSBs can strongly contribute to the development of thymic tumours characteristic of ATM deficiency." (PMID 32060399, 2020). "In summary, we can conclude that loss of TDP2 increases the incidence of the same oncogenic rearrangements that drive thymic tumour in Atm−/− animals, suggesting a strong contribution of TOP2-mediated lesions to ATM-deficient T-cell cancer predisposition." (PMID 32060399, 2020).
tuberculosis (1 paper, 2020). A chronic, recurrent infection caused by the bacterium Mycobacterium tuberculosis. "Notably, in vivo infection with Mtb led to sustained DSBs and ATM activation during chronic phase of tuberculosis." (PMID 32223892, 2020). "Hence, we propose the use of ATM inhibitors as adjunct for HDT in the treatment of tuberculosis." (PMID 32223892, 2020).
type 1 diabetes (1 paper, 2023). "Besides, ATM protein was expressed in ɣ-H2AX-expressing testicular cells and could participate in histone phosphorylation in type 1 diabetes." (PMID 38027164, 2023).
urothelial papilloma (1 paper, 2023). A rare benign condition, characterized by a papillary growth in the urinary tract with a central fibrovascular core. "In urothelial papilloma cells (RT4 line) exposed to a concentration of 100 μM, the activation of the serine/threonine kinase ataxia telangiectasia-mutated (ATM) was detected, whose known role in the response to DNA damage due to oxidative stress allowed its involvement to be predictable." (PMID 37947651, 2023).
uterine adenosarcoma (1 paper, 2025).
variant ataxia-telangiectasia (1 paper, 2023). "In one patient with normal MRI, biallelic pathogenic variants in ATM indicated variant ataxia telangiectasia." (PMID 37131188, 2023).
vitamin D deficiency (1 paper, 2021). A nutritional condition produced by a deficiency of VITAMIN D in the diet, insufficient production of vitamin D in the skin, inadequate absorption of vitamin D from the diet, or abnormal conversion of vitamin D to its bioactive metabolites. "Indeed, in vitamin D deficiency, we found a higher expression (p = 0.0044) of ataxia-telangiectasia mutated (ATM), a well-known nuclear protein involved in the initiation of oxidative stress mechanisms and DNA repair signaling." (PMID 33808491, 2021).
Xeroderma pigmentosum complementation group A (1 paper, 2012). Xeroderma pigmentosum complementation group A (XPA) is a severe form of xeroderma pigmentosum (XP; see this term), a rare photodermatosis predisposing to skin cancers. "Although not currently well defined, RASSF1A is believed to have an important role in DNA damage control as evidenced by associations with xeroderma pigmentosum complementation group A (XPA) and phosphoregulation by ATM." (PMID 22701175, 2012).